TRPV1 (transient receptor potential cation channel subfamily V member 1)
Diseases named in the same sentence as TRPV1 in open-access papers (continued):
Sharing a sentence is not in itself a finding about the gene and the disease.
viral infection (11 papers, 2016 to 2026). "The crosstalk between TRPV-1 positive nerve fibers and immune cells is critical in mediating inflammation of the airways following exposure to either inhaled allergens or viral infection." (PMID 34805220, 2021). "We wished to determine if the TRPV1 antagonist capazepine would be effective as a treatment during virus infection." (PMID 28187208, 2017). "This means that viral infection led to a phenotypic switch in many nodose Aδ fiber neurons such that they begin to express TRPV1." (PMID 27213574, 2016). "This would suggest that the response of nerve fibers already sensitive to TRPV1 stimuli, would be enhanced following the viral infection." (PMID 27213574, 2016). "Furthermore, TRPV1 inhibition with capsazepine and SB-366791 significantly reduced viral infection in vitro." (PMID 41596312, 2026). "Based on these findings, we hypothesized that TRPV1 activation—via stimuli such as heat or capsaicin—may enhance viral infection by inducing mitochondrial depolarization, which in turn promotes mitochondrial fission." (PMID 41596312, 2026). "Thus, our results and those of other studies reveal the important role of C fibers and TRPV1 in regulating host defense against viral infection, including RSV replication and inflammation." (PMID 36350149, 2022). "Interestingly, treatment with TRPV-1 antagonist in this study significantly inhibited TRPV-1 upregulation post viral infection." (PMID 34805220, 2021). "TRPA1 and TRPV1 have been implicated in the cough reflex sensitization, and they are expressed on afferent sensory airway nerves and airway epithelial cells and are activated by inhaled irritants such as OVA and virus infection." (PMID 34099759, 2021). "In this study we examined whether virus infection by these viruses in bronchial epithelial cells or neuronal cells up-regulates TRPV1, TRPA1 and ASICS3 expression." (PMID 28187208, 2017). "Based on this we reasoned that the viral infection may have led to increased capsaicin, acid and bradykinin evoked coughing by enhancing TRPV1 signaling." (PMID 27213574, 2016). "This raises the hypothesis that viral infection may lead to sensory neuroplasticity by changing TRPV1 gene expression." (PMID 27213574, 2016). "Future studies could investigate whether TRPV1 activation, for example through chronic exposure of mice to physiologically relevant, commonly consumed concentrations of capsaicin, exacerbates viral infection outcomes, thereby providing complementary insight into the role of TRPV1 in vivo." (PMID 41596312, 2026). "As we move forward, it will be crucial to explore how dietary interventions or TRPV1-targeted therapies could be leveraged to reduce viral burden and improve clinical outcomes in CVB3 and potentially other viral infections associated with EV-mediated transmission." (PMID 41596312, 2026). "Thus, viral infection of the airways may not only increase the stimulus profile of cough fibers by increasing expression of ion channels like TRPV1, but may also qualitatively change the role mediated by sensory neuropeptides in cough reflexes." (PMID 27213574, 2016). "Furthermore, the action of TRPV1 was validated in vitro using the competitive antagonist capsazepine and in vivo using the allosteric inhibitor SB-366791 which not only demonstrated reduced viral infection, but also mitigated pancreatic viral burden, inflammation and damage." (PMID 41596312, 2026). "Considered together, the data supports the hypothesis that viral infection of tracheal/bronchial epithelium leads to production of specific neurotrophins that can alter the nodose Aδ fiber and jugular C-fiber phenotype in a manner that would make them more sensitive to TRPV1 stimulation." (PMID 27213574, 2016). "More importantly, the reduced ability of TRPV1 knockout mice to develop inflammatory thermal hyperalgesia was rescued by viral infection of lumbar 3/4 DRG neurons of wild-type TRPV1, but not its SUMOylation-deficient mutant, K822R." (PMID 29670121, 2018).
viral infection (continued). "Since UV-inactivated pelleted RSV and MV preparations alone were able to increase virus up-regulation of both TRPV1 and ASIC3 receptors it was of interest to determine if cell surface Toll-like receptors (TLRs) were induced by virus infection in BEAS-2B and SHSY5Y cells." (PMID 28187208, 2017). "Since the viral infection is largely limited to larger airways, we were not surprised that we did not note an increase in TRPV1 mRNA in the nodose ganglia per se." (PMID 27213574, 2016). "In this regard, a novel approach demonstrated that optical stimulation of TRPV1 could stimulate ECFCs with unprecedented spatial and temporal resolution and with no need of viral infection." (PMID 32471282, 2020). "Whether viral infection can alter TRPV1 expression in intrapulmonary nodose neurons was not investigated here." (PMID 27213574, 2016). "Therefore, induction of cytokines by interaction of virus proteins with cell surface TLRs is a possible mechanism for up-regulation of TRPV1, ASICS3 and other related receptors without the necessity for direct virus infection." (PMID 28187208, 2017).
functional dyspepsia (10 papers, 2010 to 2025). "Functional Dyspepsia patients are hypersensitive to a capsaicin challenge, whilst a TRPV1 G315C polymorphism increases the susceptibility of developing Functional Dyspepsia." (PMID 27713376, 2010). "Furthermore, the homozygous G315C polymorphism of the TRPV1 gene has been found to be inversely related to symptom severity in functional dyspepsia patients." (PMID 21420431, 2011). "The distribution of TRPV1 immunopositivity was reported to be increased in chronic gastritis biopsies, however, in that study, control samples were collected from patients with functional dyspepsia." (PMID 32764237, 2020). "Evidence suggests that up-regulating TRPV1 may contribute to visceral hypersensitivity, which occurs through the sensitization of afferent nerve fibers in the gut that constituted a mechanism for gastric hyper‐sensitivity in functional dyspepsia." (PMID 35668782, 2022). "In the present study, it is shown that BHM may play a critical role in treating functional dyspepsia via regulating IL1B, TNF, TRPV1, SERT, and NOS3 signaling pathways." (PMID 35668782, 2022).
gout (10 papers, 2014 to 2024). A condition characterized by painful swelling of the joints, which is caused by deposition of urate crystals. "TRPV1 has been consistently implicated for playing a role in animal models of OA, RA, and gout, and has also been linked to these diseases in humans." (PMID 30326593, 2018). "However, the mechanisms underlying TRPV1 up-regulation in peripheral sensory neurons during gout are still not fully understood." (PMID 37464384, 2023). "Here, we further found TRPV1 channel functional activities were up-regulated in sensory neurons of gout model mice." (PMID 37464384, 2023). "Previous work indicated that pharmacological blocking TRPV1 is effective in reducing gout pain, joint inflammation and inflammatory cell infiltration." (PMID 37464384, 2023). "The pain-sensing TRPV1 channel makes important contributions to mechanical pain and joint inflammation in gout condition." (PMID 37464384, 2023). "Here, our results showed that pharmacological blockage of NLRP3 inflammasome remarkably attenuated TRPV1 overexpression in sensory neurons of gout mice, indicating NLRP3 inflammasome contributes to TRPV1 overexpression in gout condition." (PMID 37464384, 2023). "Eucalyptol (1,8-cineol), another TRPV1 antagonist, has demonstrated pain relief in mice with gouty arthritis, whereas the TRPV1 antagonist SB-366791 (N-(3-methoxyphenyl)-4-chlorocinn amide) exhibited pain relief in rats with tooth pain." (PMID 37569884, 2023). "While no striatal activity changes were detected throughout the time course in the gout model, TRPV1 blockage did decrease striatal CBV responses." (PMID 31451732, 2019). "Our study provides the first piece of in vivo evidence regarding activated thalamocortical nociceptive signaling through enhancing TRPV1 expression during gout attacks." (PMID 31451732, 2019). "This new information supports the development of TRPV1-based drugs for treating gout pain, while fMRI can be useful for repeated evaluation of brain activity changes induced by gout." (PMID 31451732, 2019). "The involvement of TRPV1 in gout pain was confirmed pharmacologically using a TRPV1-selective blocker called AMG9810." (PMID 31451732, 2019). "Altogether, these findings established the involvement of a TRPV1-mediated nociceptive mechanism in the augmentation of pain responses in gout." (PMID 31451732, 2019). "TRPV1 expression in DRG neurons is significantly up-regulated in gout model mice." (PMID 37464384, 2023). "TRPV1 channel has been shown to contribute to gout pain and inflammation." (PMID 37464384, 2023). "Besides TRPA1 involvement in gout, TRPV1 channels are also described as important for gout pain and inflammation." (PMID 36173505, 2022). "In contrast, our intrathecal injection eliminates the contribution from the inflammatory events at the peripheral joint and surrounding soft tissues, and therefore establishes the unique importance of TRPV1 in the nervous system in pain augmentation in gouty arthritis." (PMID 31451732, 2019). "Our hypothesis is that gout-induced change in nociceptive pathway activity may be mediated by an ion channel such as TRPV1, and results in exacerbation of pain." (PMID 31451732, 2019). "The results support the importance of central TRPV1 in modulating the pain of gouty arthritis." (PMID 31451732, 2019). "These debates complicate the potential uses of TRPV1-based drugs for treating gout pain." (PMID 31451732, 2019). "Such new information may support the development of TRPV1 antagonists as new drugs for treating gout, while fMRI can be used diagnostically for evaluating gout pain in the brain." (PMID 31451732, 2019). "Therefore, our work suggests that EA may attenuate TRPV1 overexpression in sensory neurons of gout model mice through mechanisms involving the reduction of NLRP3 inflammasome activation." (PMID 37464384, 2023). "Whether TRPV1 plays a critical role in gout pain was also explored." (PMID 31451732, 2019).
gout (continued). "Immunoprecipitation experiments indicate that TRPV1 binds significantly to β-tubulin in the affected cortical area, and thus supports the interaction between TRPV1 and neuronal structural proteins for modulating central nociceptive responses in gouty arthritis." (PMID 31451732, 2019). "If the inflammation is hot (for example, during acute gout), the neutralization of IL-1β may cause pain reduction because TRPV1 is involved whereas this treatment will not reduce the mechanical hyperalgesia in chronic RA." (PMID 25606597, 2014). "In conclusion, TRPV1, TRPM2 and TRPA1 gene knockout or pharmacological inhibition can reduce joint pain and oedema in mice with gouty arthritis." (PMID 38659380, 2024). "Our results demonstrate that EA reduces gout pain possibly through suppressing ROS-mediated NLRP3 inflammasome activation in inflamed ankle joints and TRPV1 upregulation in sensory neurons, supporting EA as a treatment option for gout pain." (PMID 37464384, 2023). "Before we used immunohistological and western blotting methods to map the distribution of TRPV1 with and without gouty arthritis, fMRI was employed first to map out the nociceptive pathway in the brain." (PMID 31451732, 2019). "However, given the success of TRPV1 agonists as topical treatments for OA, further studies on the effects of TRPA1 agonists for RA, OA, or gout are likely warranted." (PMID 30326593, 2018). "Besides TRPV1, additional proteins or other TRPV channel proteins may be assessed by similar techniques and thus add more to our understanding of gout pain in the future." (PMID 31451732, 2019). "This suggests that, in the case of intraarticular injection, the effects of TRPV1 blockage may involve reducing levels of MSU-related inflammatory factors in the tissue, and therefore this may be a confounding factor in estimating the real significance of TRPV1 in gout pain." (PMID 31451732, 2019).
ischemic stroke (10 papers, 2017 to 2025). A stroke disorder caused by obstruction of blood flow to the brain, due to thrombotic (local blood clot formation) or embolic (due to a blood clot or other material traveling from another site) event. "TRPV1 also exhibits a dual role in ischemic stroke, with both agonists and antagonists demonstrating neuroprotective potential in specific contexts." (PMID 41399206, 2025). "Capsaicin, an agonist of TRPV1, reduces neuroinflammation in ischemic stroke, MS, AD, and PD, which improves the outcomes of animal models of these diseases." (PMID 41399206, 2025). "Our data revealed enhanced spiking activity after activation of mechanosensitive Piezo1 channels in trigeminal afferents of the IL hemi-skulls of the ischemic stroke group, as well as prolonged activation of nociceptive TRPV1 channels." (PMID 36293444, 2022). "Our data suggest the involvement of mechanosensitive Piezo1 channels capable of maintaining high-frequency spiking activity and of nociceptive TRPV1 channels in trigeminal headache pain responses after experimental ischemic stroke in mice." (PMID 36293444, 2022). "Our results involve the effect of TRPV1 in the autophagy and apoptosis of microglia induced by oxidative stress injury, and the elucidation of its mechanism would illuminate the way to ischemic stroke prevention and treatment." (PMID 34336554, 2021). "TRPV1 or TRPV4 inhibition has been applied in treating ischemic stroke via preserving the BBB permeability in various in vitro and/or in vivo experiments, while TRPV2, the most expressed isoform in human BBB, is much less studied." (PMID 33806707, 2021). "TRPV1 was also found to be involved in ischemic stroke and neurological deficits in a murine model of middle cerebral artery occlusion." (PMID 33002009, 2020). "In this study, we investigate the effects of TRPV1-mediated hypothermia by DHC on long-term ischemic stroke injury and functional outcome." (PMID 29247238, 2017). "Our findings validate the benefit of TRPV1-mediated hypothermia for treatment of ischemic stroke injury." (PMID 29247238, 2017). "Importantly, another survey has found that acupuncture at the Baihui (DU20) and Sanyinjiao (SP6) had a role in ameliorating ischemic stroke through neuroprotective effects with anti-inflammation and TRPV-1-mediated antioxidant stress function." (PMID 33178314, 2020). "While the mechanism underlying the structural protection of the BBB was not explored following TBI, anandamide has been found to decrease BBB permeability in a model of ischaemic stroke by transient receptor potential cation channel, subfamily V, member 1 (TRPV1)." (PMID 28261100, 2017).
astrocytomas (9 papers, 2016 to 2023). "Previously, it was observed that arvanil caused TRPV1-dependent Ca2+ response and cell death in high-grade astrocytoma in vitro." (PMID 36430670, 2022). "CBG more than CBD binds and dilates transmembrane TRPV1 Ca2+ permeable pores and thus more or less desensitizes TRPV1 and perturbs its signalling activity in high grade astrocytoma and NSCs." (PMID 36497400, 2022). "Neural precursor cell-derived endovanilloids and Arvanil, a TRPV-1 agonist, induces cell death in high-grade astrocytoma via the TRPV-1-mediated activating transcription factor-3 endoplasmic reticulum stress pathway." (PMID 26888607, 2016). "Notably, TRPV1 expression was found to be elevated in high-grade astrocytoma tissues compared with normal brain tissues." (PMID 37569884, 2023). "NPCs in proximity are the main sources of releasing the endogenous TRPV1 agonist, so TRPV1 may be a potential target for therapy in high-grade astrocytomas." (PMID 35887116, 2022). "Using paraffin immunohistochemistry, TRPV1 and TRPA1 protein expression was found in 62% of the WHO grade II astrocytomas, 37.5% of the anaplastic astrocytomas (WHO grade III), and 16.3% of GBM cases." (PMID 37240443, 2023). "In addition, stimulation of TRPV1 could activate ATF3‐ER stress pathway, and help neural precursor cells to induce the cell death of high‐grade astrocytomas." (PMID 38093622, 2023).
chronic obstructive pulmonary disease (9 papers, 2019 to 2023). A chronic and progressive lung disorder characterized by the loss of elasticity of the bronchial tree and the air sacs, destruction of the air sacs wall, thickening of the bronchial wall, and mucous accumulation in the bronchial tree. "A recent study has shown that tiotropium acts on the afferent sensory nerves and inhibits TRPV1-mediated effects unrelated to its anticholinergic activity and may also provide some clinical benefit in controlling chronic obstructive pulmonary disease (COPD) and asthma." (PMID 32039252, 2019).
Crohn disease (9 papers, 2008 to 2025). A gastrointestinal disorder characterized by chronic inflammation involving all layers of the intestinal wall, noncaseating granulomas affecting the intestinal wall and regional lymph nodes, and transmural fibrosis. "Notably, TRPV1 is also up regulated in several human pathological conditions including vulvodynia, GI inflammation, Crohn’s disease and ulcerative colitis." (PMID 27322240, 2016). "In the ileum, TRPV1 mRNA levels were decreased in never smoking Crohn’s disease patients compared to healthy subjects (p <0,001; n = 20/group)." (PMID 32760089, 2020).
skin tumors (9 papers, 2016 to 2023). "Compared to healthy cells, TRPV1 mRNA and/or protein expression levels are downregulated in many cancerous tissues, including colorectal, nervous system, endometrial, renal and skin cancers." (PMID 32545311, 2020). "It is therefore relevant that capsaicin upregulates the mRNA and protein expression of TRPV1 in certain healthy and cancerous (e.g., nasopharyngeal and skin cancer) cell lines." (PMID 32545311, 2020). "Meanwhile, study suggested that skin cancer may be closely related to TRPV1 and TRPV1 knockout mice were facile to induce skin carcinogenesis." (PMID 30881453, 2019). "Early studies suggested that TRPV1 was involved in skin cancer." (PMID 30881453, 2019). "Some studies have provided evidence suggestive of a connection between TRPV1 and skin cancer." (PMID 27983625, 2016). "Thus, even if we could show that TRPV1 shows a higher expression level in all our investigated tumors, further studies need to be conducted to better understand the exact role of TRPV1 in skin tumor formation to use it as a potential therapeutic target." (PMID 34199609, 2021). "Interestingly, the results found on prostate and skin cancers cells have shown that both TRPV1 and TRPV2 are involved in cancer progression, thanks to their ability to interact with G-proteins and, therefore, to interfere with intracellular signaling and to modulate intracellular Ca2+." (PMID 30627539, 2018). "In our study, we investigated the expressions of ASIC1, ASIC2, TRPV1 and TRPV4 in common skin tumors, namely SCC, BCC, NCN and MM." (PMID 34199609, 2021). "We conducted immunohistochemistry using paraffin-embedded tissue samples from patients and found that most skin tumors express ASIC1/2 and TRPV1/4." (PMID 34199609, 2021). "Using a skin carcinogenesis model with 7,12-dimethyl benz(a)anthracene (DMBA) and TPA in TRPV1−/− (knockout) and TRPV1+/+ (wild type) mice, authors have shown that TRPV1−/− mice developed significantly more skin tumors than TRPV1+/+ mice." (PMID 29258175, 2017). "ASIC1, ASIC2, TRPV1 and TRPV4 in skin tumors might be involved in tumor progression, thus being potential diagnostic and therapeutic targets." (PMID 34199609, 2021). "In conclusion, ASIC1, ASIC2, TRPV1 and TRPV4 are expressed by most common skin tumors." (PMID 34199609, 2021). "Thus, no role for TRPV1 in skin cancer has yet been definitively established." (PMID 27983625, 2016).